ARG1 (arginase 1)
Diseases named in the same sentence as ARG1 in open-access papers (continued):
Sharing a sentence is not in itself a finding about the gene and the disease.
asthma (50 papers, 2007 to 2026). "Similar to Arg1, Arg2 expression is increased in people with asthma caused by chronic airway inflammation." (PMID 39952693, 2025). "This specific delivery resulted in a significant knockdown of ARG1 gene expression, indicating successful interference with the gene upregulation associated with airway remodeling in asthma." (PMID 39896757, 2025). "In genetic association studies of asthma, we considered the role of SNP by SNP interactions when determining independence of signals for SNPs in the ARG1 gene and bronchodilator response." (PMID 33669563, 2021). "Itwas found that the rs2781667*C allele of the ARG1 gene is a marker of an increased risk of asthma in Tatars." (PMID 33659822, 2020). "It was foundthat the rs2781667*C allele of the ARG1 gene is a markerof increased risk of asthma development in Tatars." (PMID 33659822, 2020). "Anassociation of the rs2781666*T allele and CT haplotype(rs60389358, rs2781666) of the ARG1 gene with asthma anda considerably higher level of serum arginase was establishedin asthma patients from India." (PMID 33659822, 2020). "Vonk J.M., Postma D.S., Maarsingh H., Bruinenberg M., KoppelmanG.H., Meurs H. Arginase 1 and arginase 2 variations associatewith asthma, asthma severity and β2 agonist and steroidresponse." (PMID 33659822, 2020). "In addition, we considered the role of SNP by SNP interactions when determining independence of signals for SNPs in the ARG1 gene and bronchodilator response in genetic association studies of asthma." (PMID 33669563, 2021). "Beta-2-agonists are some of the major class of bronchodilators used for asthma management.According to published data, allelic variants of the arginase ARG1 and ARG2 genes are associated with a risk ofasthma development, spirometry measures and efficacy of bronchodilator therapy." (PMID 33659822, 2020). "We investigated whether Arg1 ablation in the lung affected the expression of asthma-associated cytokines." (PMID 29183288, 2017). "Furthermore, single nucleotide polymorphisms of arginase 1 have been specifically associated with responsiveness to bronchodilators, and L-arginine bioavailability can impact airflow in asthma." (PMID 21291525, 2011). "Arginase-1 in macrophages is induced by Th2 type cytokines such as IL-4, IL-10, IL-13 and IL-21 and increased arginase is associated with resistance to worm infections, allergic conditions such as asthma and Th2 induced pathologies." (PMID 19696894, 2009). "NOS2 has multiple roles in the airways, its expression being highest in severe asthma, while ARG1 decreases." (PMID 39466641, 2025). "NOS2 was significantly increased after infection in patients with asthma compared to the controls, while ARG1 was downregulated in patients with asthma." (PMID 39466641, 2025). "Given its pivotal role in various facets of airway remodeling, Arg1 is a potential therapeutic target in asthma." (PMID 39896757, 2025). "In fact, an upregulation of Arg1 has been found in pulmonary diseases, including chronic obstructive pulmonary disease, pulmonary hypertension, pulmonary fibrosis, tuberculosis, and asthma." (PMID 39952693, 2025). "In this investigation, we used isoprenaline as a reliever and ARG1 small interfering RNA (siRNA) as a controller and preventer of airway remodeling in a combination treatment for asthma." (PMID 39896757, 2025). "Arginine metabolism is important in type 2 high airway inflammation and asthma, generating NO by several enzymes, including inducible nitric oxide synthase (iNOS), arginase-1 (ARG1), and ARG2." (PMID 38555460, 2024). "Arginase 1 (Arg1), a nitric oxide substrate that regulates bronchomotor tone and inflammation, plays a significant role in asthma development." (PMID 36834405, 2023). "Adoptive transfer of MDSC or induction of those cells has been shown to dampen airway inflammation in a mouse-model for asthma through Arginase-1 and NO synthase-2." (PMID 37428185, 2023).
asthma (continued). "ARG1 can be released to the extracellular microenvironment during inflammatory conditions, e.g., asthma and infectious diseases." (PMID 37261353, 2023). "In this study, in comparison to M2 macrophages, LPS/IL-4-induced macrophages showed increased expression of Arg1 whose protein involves in deposition of collagenous and extracellular matrix components in lung parenchyma to make asthma severe." (PMID 37180123, 2023). "To determine the effects of IL-31 on the expression of asthma-associated genes, we quantified the expression of genes associated with inflammation (IFNγ, TNF-α, IL-6, and IL-17) and Th2 responses (IL-4, IL-13, ARG1, MUC4, and MUC5AC)." (PMID 38081868, 2023). "The vast majority of pharmacogenetic studies involving ARG1 andARG2 concentrate on response to drugs used in asthma." (PMID 36264109, 2022). "M2 macrophages, characterized by their expression of Mrc1, Arg1, and Chil3 are well-qualified candidates as they secrete IL-13, are known to activate T cells and are upregulated in the blood of asthma patients." (PMID 35697721, 2022). "Former literatures identified the upregulation of Arg1 in the submucosal inflammatory cell of asthma patients." (PMID 35153740, 2021). "Previously, we showed that adoptive transfer of MDSCs dampens lung inflammation in murine models of asthma through cyclooxygenase-2 and arginase-1 pathways." (PMID 34322123, 2021). "The mRNA levels of MGL and ARG1 were also significantly higher in the asthma group than in the control group, but they were not significantly correlated with sputum TG2 expression in asthma patients." (PMID 33945658, 2021). "The mean fluorescence intensity (MFI) of Arg-1 and iNOS from G-MDSCs in the asthma group was higher than that in the normal group." (PMID 32549755, 2020). "The balance between iNOS and Arg1 is required to maintain the normal muscle tone, and this explains a possible role of elevated Arg1 expression during asthma and how it stimulates bronchoconstriction." (PMID 32024540, 2020). "Litonjua A.A., Lasky-Su J., Schneiter K., Tantisira K.G., Lazarus R.ARG1 is a novel bronchodilator response gene: screening andreplication in four asthma cohorts." (PMID 33659822, 2020). "Induction of experimental asthma increased arginase 1 expression in lungs dramatically, as observed previously." (PMID 29792217, 2018). "On the contrary, macrophage-specific arginase 1 is not essential in multiple murine models of Th2 lung inflammation and asthma, suggesting that the regulatory outcomes of macrophage-derived arginase 1 are organ specific." (PMID 28223985, 2017). "Therapeutic inhibition of arginase-1 has been shown to have beneficial effects for other diseases, such as asthma, cancer, and parasitic infections, and shows potential as a therapeutic target to explore in fungal diseases." (PMID 28119468, 2017). "Since Th2 responses predominate in asthma and lung and airway inflammation the IL-4/13-IL-4Rα-Stat6 pathway is anticipated to drive Arg1 expression in these diseases, and an increase in Arg1 is associated with many types of lung inflammation." (PMID 23637937, 2013). "Arg1+ AAMs abound in Th2-dominated diseases such as asthma, atopic dermatitis, and helminth and other parasite infections." (PMID 23637937, 2013). "Arginase 1 (Arg1) expressed by Th2-induced fibroproliferative M2 macrophages is also up-regulated during OVA-induced asthma, but down-regulated during post-pneumonectomy lung regeneration." (PMID 19804646, 2009). "The qRT-PCR analysis of these samples verified results for Ccl8 and indicated a down-regulation of 10 other asthma-related genes (Arg1, Ccl11, Ccl24, Ear11, Mcpt1, Sprr2a, Chi3l3, Chi3l4, Chia, Slc7a2) in EOO versus AOO mice." (PMID 18087596, 2007). "Among the up-regulated genes were 3 associated with inhibition of proliferation (Gpnmb, Setd8, Runx2) and 1 promoting inflammatory and immune responses (Pik3cd), as well as 4 asthma-related genes (Arg1, Ccl24, Slc7a2, Mcpt1) identifiable only through qRT-PCR." (PMID 18087596, 2007).
asthma (continued). "However, in asthma, as a cytokine of the T helper immune response, ARG1 is highly expressed in epithelial cells, endothelial cells, and macrophages in the lung tissue airways and contributes to airway tissue remodeling." (PMID 39896757, 2025). "Our results suggest that Arg1 may play a similar role in the immune regulation of asthma in Meishan pigs, and further studies are needed to elucidate its detailed mechanism." (PMID 39858200, 2025). "Conversely, the asthma-induced group exhibited significantly elevated ARG1 gene expression." (PMID 39896757, 2025). "However, the ARG1 siRNA/PEI–isoprenaline complex treatment group demonstrated a significant decrease in ARG1 gene expression, with ARG1 expression suppressed by approximately 63% compared with that of the untreated asthma group." (PMID 39896757, 2025). "Our study found that the expression of Arg1 and related genes may be involved in the immune regulation of asthma in Meishan pigs." (PMID 39858200, 2025). "Furthermore, to examine the therapeutic effects of increased arginase-1 expression we decided to include a single dose of BCT-100, a pegylated recombinant arginase-1, as an in vivo therapy in a murine model of asthma." (PMID 34322123, 2021). "However, the anti-inflammatory effect of EP4 agonism through arginase-1 needs to be confirmed using a selective arginase-1 inhibitor in an asthma model." (PMID 34322123, 2021). "Arginase genetic polymorphisms (rs2781667 of the ARG1 gene, rs17249437, rs3742879,rs7140310 of the ARG2 gene) were studied in 236 children with asthma and 194 unrelated healthy individualsof Russian, Tatar and Bashkir ethnicity from the Republic of Bashkortostan." (PMID 33659822, 2020). "ARG1 and CHIL3 are well-recognized susceptibility genes closely associated with childhood asthma that increase AHR and weaken lung function; additionally, the polymorphic and epigenetic states of ARG1 are associated with childhood asthma progression." (PMID 31133848, 2019). "Upregulated arginase-1 has also been demonstrated in patients with diabetes and in patients with heart failure, postulating another common disease mechanism with asthma." (PMID 27212806, 2016). "In patients with asthma, Arg-1 mRNA expression is increased in sub-mucosal inflammatory cells." (PMID 25905462, 2015). "AAMs modulate T cell and wound healing responses and Arg1 might contribute to asthma pathogenesis by inhibiting nitric oxide production, regulating fibrosis, modulating arginine metabolism and restricting T cell proliferation." (PMID 23637937, 2013). "Thus, we argue that increased expression of Arg1 in macrophages during asthma and lung inflammation is a consequence of a pre-set activation program necessary to combat a wide variety of parasites (especially worms) in a tissue-specific way." (PMID 23637937, 2013). "However, the few asthma/inflammatory genes that are differentially expressed (Pik3cd, Arg1, Slc7a2, Ccl24, Mcpt1) are all up-regulated in ETS-exposed mice." (PMID 18087596, 2007). "However, when examined by qRT-PCR, four asthma-related genes were identified as up-regulated (Arg1, Ccl24, Slc7a2, Mcpt1)." (PMID 18087596, 2007). "Up-regulation of ARG1 has been identified as an important step in the pathophysiology of asthma." (PMID 17450223, 2007). "Furthermore, for the first time we showed that arginase-1 therapy may have beneficial effects in asthma." (PMID 34322123, 2021). "Arginase 1 impact in asthma might be associated to a greater extent with other, non-NO related, reactions conditioned by this enzyme." (PMID 31683763, 2019). "Since the asthmatic responses in mice and humans show similar sex-related differences, and since ablation of Arg1 did improve peripheral lung function in male mice only, we hypothesize that treatment of asthma by modulating arginase activity in the lung will primarily benefit male patients." (PMID 29183288, 2017).
asthma (continued). "Additionally, gene therapeutic approaches similar or distinct from those tested recently can be attempted and will allow for the study of the exciting roles for Arg1 in immune function, as well as in the pathophysiology of cardiovascular disease, asthma and cancer." (PMID 24224027, 2013). "Four genes linked to asthma or lung inflammation (Arg1, Ccl24, Slc7a2, Mcpt1) that did not pass all the microarray filtering criteria were confirmed by qRT-PCR as being up-regulated in ESO versus ASO mice, which is consistent with an enhanced lung response in ETS-exposed mice." (PMID 18087596, 2007). "Mitochondrial reactive oxygen species, glutathione S-transferases, arginase 1 and RORC in immune regulation, the Notch pathway, YPEL4 in cell proliferation, and MARCKS in airway mucus secretion play roles in asthma pathogenesis." (PMID 39858200, 2025). "Arginase-1 (ARG1), a key player in allergic asthma, is overexpressed during abnormal activation of the T helper 2-mediated immune response in asthma." (PMID 39896757, 2025). "In the mouse model of asthma consisting of NOS2 knockout mice, allergen challenge upregulated protein levels of ARG1 and ARG2 40-fold and 4-fold, respectively." (PMID 36061615, 2022). "It has been shown that both ARG1 and ARG2 are expressed in the airways and are upregulated in animal models of asthma as well as in patients." (PMID 36061615, 2022). "On thecontrary, some studies did not detect a significant associationof ARG1 gene polymorphisms with the efficacy of asthmatherapies.Together, this results and literature data confirm that ARG1gene allelic variants can contribute to asthma pathogenesisand the effectiveness of disease therapy." (PMID 33659822, 2020). "In this paper, we analyzedassociations of arginase ARG1 (rs2781667) and ARG2(rs17249437, rs3742879, rs7140310) gene polymorphismswith asthma development and course and with sensitivity totherapy in patients." (PMID 33659822, 2020). "This was further corroborated in a guinea pig animal model of asthma, where application of the Arg1 inhibitor nor-NOHA fully reversed the disease." (PMID 37275910, 2023). "Another mechanism that may affect development of asthma in response to NOS inhibition is increased availability of L-arginine, the starting substance of NO to arginase-1/arginase-2 resulting in increased production of polyamines and proline." (PMID 27212806, 2016). "Although an association between ARG1 polymorphisms and the level of CRP has not been reported, associations of ARG1 polymorphism with CVD and asthma have been reported." (PMID 24763700, 2014). "The good correlation of TG2 with CD206 but not with MGL or ARG1 suggests that TG2 and CD206 might belong to the same M2 subtype in association with asthma pathogenesis." (PMID 33945658, 2021). "This hypothesis may explain why deleting Arg1 in macrophages does not alter Th2-mediated lung inflammation or pathology while arginase inhibitors or siRNA nonetheless ameliorate some features of asthma." (PMID 23637937, 2013).
colitis (49 papers, 2014 to 2025). Inflammation of the colon. "The top drugs that show potential selectivity for ARG1 are associated with treating fungal and bacterial infection, arthritis, colitis, cancer, depression, and hypertension." (PMID 36014374, 2022). "Because of the observedincrease in the expression of ARG1 in the colon of gp130757F/Fmice, we next focused our attention on the roleof MDSCs in decreased colitis susceptibility of gp130757F/Fmice." (PMID 26848037, 2016). "Collectively, these results showed that G-MDSC exo can inhibit DSS-induced colitis, and this was associated with Arg-1 activity-mediated suppression of Th1 cells and Tregs expansion." (PMID 26885611, 2016). "Butyrate attenuated intestinal inflammation in mice with dextran sulfate sodium (DSS)-induced colitis, with a significant increase in colonic expression of the M2 macrophage-associated protein, Arg1." (PMID 27094081, 2016). "Additionally, the levels of the transcripts encoding arginase 1 (Arg1) and tumor necrosis factor super family 14 (Tnfsf14; Light), which are anti-inflammatory during colitis, were also significantly decreased in infected Tln1Δmye colon tissues." (PMID 38102166, 2023). "Our results showed that the increased mRNA level of FOXP3 in colitis tissues may be associated with significantly upregulated Arg-1." (PMID 36713833, 2023). "Here we show that IL-17KO mice had increased susceptibility to DSS-induced colitis which was associated with decrease in expression of mRNAs implicated in M2 and/or wound healing macrophages, such as IL-10, IL-1 receptor antagonist, arginase 1, cyclooxygenase 2, and indoleamine 2,3-dioxygenase." (PMID 25254662, 2014). "STAT3 and NF-κB upregulated the expression of arginase 1 (ARG1) and inducible nitric oxide synthase (iNOS), the main suppressors of MDSCs in murine colitis induced by dinitrobenzene sulfonic acid (DNB) or DSS." (PMID 40244120, 2025). "In DSS colitis, Arg-1 deletion in myeloid cells attenuated the protective role of MDSCs during colitis by upregulating IL-17A and IL-17F, while the adoptive transfer of suppressive MDSCs alleviated colitis in ArgmyeKO mice." (PMID 40244120, 2025). "Macrophages isolated from the intestinal mucosa of TNBS-induced colitis mice showed increased mRNA levels of iNOS and IL-12p40 (M1 polarization markers) and decreased mRNA levels of IL-10 and Arg-1 (M2 polarization markers) compared with control mice." (PMID 38796413, 2024). "Arg-1+ MDSCs have even modulated Th17 cell polarization to enhance IL-17A secretion, thereby attenuating the immune response and alleviating colitis." (PMID 37733169, 2024). "Studies have shown that G-MDSC exosomes attenuate DSS-induced colitis by inhibiting Th1 cell proliferation and promoting Treg cell expansion, which is related to Arg-1 activity." (PMID 36713833, 2023). "There are data indicating that EVs modulate macrophage polarization from M1-type to M2-type in the colonic tissue from DSS colitis mice through the enhancement of enhanced Arg-1 and CD206 expression in colon macrophages." (PMID 36012170, 2022). "A polarization toward M2 macrophages is characterized by an increase in several markers, including arginase 1 (Arg-1) and Fizz, which were found to be increased in experimental colitis." (PMID 35628317, 2022). "Schematic diagrams for the mechanisms of MDSC-derived Arg-1 in the polarization of TH17 cells in DSS-induced colitis mouse model." (PMID 32391010, 2020). "Together, these results suggested that Arg-1 deletion attenuates a protective role of MDSC during colitis by dichotomously regulating IL-17A and IL-17F levels in the colorectum, thus contributed to the exacerbation of colitis." (PMID 32391010, 2020). "Collectively, MDSC-derived Arg-1 promotes IL-17A expression in the colorectum, inhibits IL-17F expression and greatly relives colitis in mice." (PMID 32391010, 2020).